MBD2 (methyl-CpG binding domain protein 2)
Diseases named in the same sentence as MBD2 in open-access papers (continued):
Sharing a sentence is not in itself a finding about the gene and the disease.
asthma (continued). "Serum MBD2 and MPO levels were higher in patients with Th17 severe asthma compared to patients with T2 severe asthma (P < 0.001), but serum ECP levels were lower in patients with Th17 severe asthma compared to those with T2 severe asthma (P = 0.003)." (PMID 34692717, 2021). "Moreover, MBD2 was positively correlated with Th17 cells and MPO, which is of great significance for the clinical diagnosis and treatment of Th17 severe asthma." (PMID 34692717, 2021). "We also confirmed that MBD2 levels are positively correlated with MPO and Th17 cells but negatively correlated with FEV1/ FVC, FEV1%predicted, Th2 cells and ECP in patients with severe asthma." (PMID 34692717, 2021). "Although little is known about epigenetic regulation in neutrophils-dominant asthma, in our study we report that MBD2 expression in splenic CD4+ T cells and lungs from neutrophils-dominant asthma mice was significantly higher compared to conventional asthma mice and the control group." (PMID 30150897, 2018). "Understanding the role of MBD2 and HIF-1α in neutrophils-dominant asthma may offer a theoretical basis for treatment." (PMID 30150897, 2018). "This indicates that MBD2 can participate in the differentiation of Th17 cells and IL-17 secretion through IRF4 expression and so participate in the pathogenesis of the neutrophil-predominant severe asthma model." (PMID 28808358, 2017). "At present, there is little research on the role of MBD2 in severe asthma, and the relationship between MBD2 and IRF4 in severe asthma is not known." (PMID 28808358, 2017). "Severe asthma+ DHT/E2 did not reduce MBD2 to the level of severe asthma+ DHT." (PMID 36062195, 2022). "Next, to further understand the molecular mechanism of MBD2 involvement in Th17-dominant asthma, we attempted to determine whether there was any relationship between MBD2 levels and MINK1 expression in BECs exposed or not exposed to HDM + LPS." (PMID 36303542, 2022). "The severe asthma+ DHT/E2 group did not reduce MBD2 to the level of severe asthma +DHT." (PMID 36062195, 2022). "However, silencing/OE of MBD2 in severe asthma+ DHT group did not significantly change the GATA3 detection within the group." (PMID 36062195, 2022). "However, biomarkers for Th17 severe asthma have not been reported, and serum MBD2 levels in asthmatic patients have not been reported in the literature." (PMID 34692717, 2021). "Next, we needed to analyze whether MBD2 can affect IRF4 and participate in asthma." (PMID 28808358, 2017). "In addition, these results indicated that Th17 cells are not directly downstream of MBD2, and MBD2 regulates Th17 cell differentiation through negative regulation of MINK1 expression, thus mediating the onset of Th17-dominant asthma." (PMID 36303542, 2022).
autoimmune disease (7 papers, 2016 to 2025). A disorder resulting from loss of function or tissue destruction of an organ or multiple organs, arising from humoral or cellular immune responses of the individual to their own tissue constituents. "Dysregulated MBD2 expression has been linked to various pathological conditions, including autoimmune diseases and cancers." (PMID 40533455, 2025). "If validated, MBD2 inhibition could offer a promising approach to treating the epigenetic defects associated with a range of autoimmune disorders." (PMID 40533455, 2025). "Moreover, the application of AI tools to develop small-molecule inhibitors targeting MBD2, as well as other demethylases and demethylase-associated proteins, is crucial for advancing therapeutic strategies in autoimmune diseases." (PMID 40533455, 2025). "As a DNA methylation reader, Methyl-CpG-binding domain protein 2 (MBD2) has been extensively studied in the contexts of innate immunity, adaptive immunity, and autoimmune diseases." (PMID 40467564, 2025). "Current research primarily focuses on MBD2 in cancer, with less emphasis on its role in autoimmune diseases." (PMID 40533455, 2025). "Furthermore, it highlights the mechanistic contributions of MBD2 to autoimmune diseases such as systemic lupus erythematosus and evaluates its potential as a novel therapeutic target for these conditions." (PMID 40533455, 2025). "This suggests that MBD2 may ultimately contribute to DNA hypomethylation and aberrant gene expression in peripheral T cells of patients with autoimmune diseases by modulating DNA methylation levels and patterns, and inhibiting gene transcription." (PMID 40533455, 2025). "Recent studies also suggest that MBD2 may play a key role in DNA demethylation in lupus and other autoimmune disorders." (PMID 40533455, 2025). "However, the specific mechanisms by which MBD2, an important component of DNA methylation, contribute to different autoimmune diseases and its role in various immune cells remain unclear." (PMID 40533455, 2025). "Investigating the TFs regulating the fine‐mapped autoimmune disease enhancers, we find the known immune response TFs NFKB1/2, RELB and IRF8, but also MBD2, ZBT14 and PURA, which we identified as important TFs for predicting response to infection." (PMID 37073532, 2023). "What’s more, MBD2 was found to stimulates Th17 cell differentiation and IL-17 release in other autoimmune diseases and IL-17 play critical functions in the pathophysiology of SLE So, MBD2 might play important roles in SLE progression." (PMID 31412880, 2019). "The increased expression of MBD2 and MBD4 in the AAA group was also consistent with the increased rate of DNA methylation, further enhancing the main function of regulatory T cells to inhibit autoimmune diseases." (PMID 31001930, 2019). "In human patients, increased levels of MBD2 and global demethylation in CD4+ T cells has been observed in several autoimmune disorders, including systemic lupus erythematosus, systemic sclerosis, dermatomyositis and MBD2 was determined to be a susceptibility locus for psoriasis." (PMID 27303433, 2016).
systemic lupus erythematosus (7 papers, 2013 to 2025). An autoimmune multi-organ disease typically associated with vasculopathy and autoantibody production. "MBD2 deficiency effectively attenuated lupus-like symptoms and reduced the GC responses in lupus mice." (PMID 40467564, 2025). "What’s more, MBD2 deficiency effectively attenuated lupus-like symptoms, reduced the germinal center responses, and decreased anti-dsDNA antibodies in lupus model mice." (PMID 40467564, 2025). "Further analysis focused on whether MBD2 deficiency attenuates lupus symptoms by suppressing humoral immunity in SLE development." (PMID 40467564, 2025). "This study further discovered that in lupus patients experiencing nephritis, expression levels of MBD2 in DN B cells, PBC cells, and general B cells were markedly higher compared to those in patients without nephritis." (PMID 40467564, 2025). "Significantly elevated MBD2 mRNA levels were observed in T cells from lupus patients, with a positive correlation between genomic hypermethylation and MBD2 mRNA levels." (PMID 40533455, 2025). "In our study, we found that MBD2 expression in B cells from lupus patients and lupus-like mice was increased and correlated with patient disease activity." (PMID 40467564, 2025). "Specifically, active lupus patients show lower methylation levels compared to inactive patients, while MBD2 expression is significantly higher in lupus patients." (PMID 40533455, 2025). "However, this research contributes valuable insights into the involvement of MBD2 in lupus and underscores the potential of B-cell targeted therapies in treating lupus patients." (PMID 40467564, 2025). "However, while current studies primarily focus on clinical statistics, the mechanisms by which MBD2 contributes to the pathogenesis of lupus remain insufficiently explored." (PMID 40533455, 2025). "In addition, MBD2 mRNA and protein expression levels were increased in peripheral blood B cells of lupus patients and splenic B cells of cGVHD model mice (referred to as the Bm12 model)." (PMID 40467564, 2025). "It was found that elevated MBD2 mRNA levels in CD4+ T cells of systemic lupus erythematosus (SLE) patients were positively correlated with the SLE disease activity index." (PMID 36303542, 2022). "However, the regulation of PI3K by DNA methylation and the role of MBD2 in lupus remain unclear." (PMID 40467564, 2025). "It would be of interest to investigate whether MBD2 inhibitors can reverse the demethylation of cytokines and other genes in CD4+ T cells from lupus patients." (PMID 40533455, 2025).
Autoimmunity (6 papers, 2016 to 2025). The occurrence of an immune reaction against the organism's own cells or tissues. "In fact, loss of MBD2 is protective against experimental autoimmune encephalomyelitis, a model of T cell mediated autoimmunity and demyelinating diseases of the central nervous system." (PMID 27303433, 2016). "Therapeutic targeting of MBD2 demonstrates potential to correct epigenetic dysregulation in autoimmunity, with preclinical studies identifying tractable strategies for clinical translation." (PMID 40533455, 2025). "MBD2 maintains the homeostasis of the Th1 program by binding to methylated CpG DNA within the Stat1 promoter, thereby preventing autoimmunity." (PMID 40533455, 2025). "Alterations in DNA methylation and MBD2 expression can influence the maintenance of Th1 program homeostasis, via the binding of MBD2 to methylated CpG DNA within the Stat1 promoter, thereby preventing autoimmunity." (PMID 37742034, 2023). "Surprisingly, MBD2-deficient mice did not develop autoimmunity, possibly because their T effector cells were insensitive to stimulation and susceptible to Treg suppression." (PMID 34692717, 2021). "Although loss of MBD2 results in reduced numbers of Treg cells, Mbd2 null mice surprisingly do not develop autoimmunity, perhaps because their T effector cells are less responsive to stimulation and more susceptible to Treg suppression." (PMID 27303433, 2016). "Together, our findings suggest that MBD2 directly binds to the methylated CpG DNA within the Stat1 promoter to suppress its transcriptional activity, thereby maintaining the homeostasis of the Th1 program in CD4 T cells to prevent organ-specific autoimmunity." (PMID 34420035, 2022). "Given the fact that MBD2 itself does not affect DNA methylation, rather by interpreting the effect of DNA methylation changes, our data support that MBD2 acts as a repressor to maintain the homeostasis of the Th1 program, by which it prevents autoimmunity in the T1D setting." (PMID 34420035, 2022).
colorectal cancer (6 papers, 2006 to 2019). A primary or metastatic malignant neoplasm that affects the colon or rectum. "The loss of MBD2 function causes downregulation of the Wnt signaling pathway which plays a major role in the development of colorectal cancer." (PMID 31245293, 2019). "Like Mbd3, other Mbd proteins, especially Mbd2 and Mbd4, are associated with progression of cancer such as colorectal cancer, albeit by different mechanisms." (PMID 28467410, 2017). "All other neighboring genes, including MBD2, are rarely affected by hypermethylation or point mutations in colorectal cancer." (PMID 27303433, 2016). "To investigate the relevance of MBD2 in human intestinal cancer, we looked for evidence that it is preferentially retained in colorectal cancer, and whether its loss is associated with a positive prognosis." (PMID 29603746, 2018). "MBD2 has been studied particularly in the context of colorectal cancer, but questions remain as to the specific role of MBD2 in tumor initiation or progression." (PMID 27303433, 2016). "Moreover, knockout of Mbd2 gene mice protected against tumorigenesis when crossed with ApcMin/+ mice (a rodent model for colorectal cancer)." (PMID 31245293, 2019). "Moreover, antisense oligonucleotides against MBD2 gene decreased tumorigenesis in human lung and colorectal cancer cells both in vitro and in vivo." (PMID 31245293, 2019). "The finding that the 18q21 locus that includes MBD2 is deleted in 70% of human colorectal cancers led to speculation that MBD2 itself could be a candidate tumor suppressor gene." (PMID 27303433, 2016). "The DCC (deleted in colorectal carcinoma), proximal to MBD2, is the largest gene in this region, but no statements about its expression can be made because of a lack of informative expression measures." (PMID 16982006, 2006). "While these results suggest targeting MBD2 may have therapeutic potential for colorectal cancer, further investigations show that the downregulation of Wnt signaling may be attributed to general disruption of chromatin regulation rather than MBD2-specific functions." (PMID 27303433, 2016).
prostate carcinoma (6 papers, 2011 to 2023). A carcinoma that arises from epithelial cells of the prostate gland. "For example, MBD2 is associated with cancer-related methylations in prostate cancer, and it is also interrelated to chronic myeloid leukemia." (PMID 35785161, 2022). "MBD2 plays an important role in cancer by silencing key tumor suppressor genes in prostate cancer, colon cancer, and liver cancer." (PMID 31245293, 2019). "Interestingly, MBD2 has been also shown to function in the maintenance and spread of DNA methylation at specific regulatory regions of prostate cancer cells." (PMID 31245293, 2019). "Furthermore, Western blot analysis demonstrated that saffron treatment induced changes in the expression of other key genes (DNMT1, DNMT3b, MBD2, CD44, HDAC3, c-Myc, NF-kB, TNFα, AR, N-RAS, and PTEN) in prostate cancer cells." (PMID 38201944, 2023). "We have also shown that targeting methyl-CpG-binding domain protein 2 (MBD2), a protein that can read the DNA methylation marks and is frequently upregulated in many cancers, using a 20-mer antisense oligonucleotide (ASO) reduced uPA gene expression in breast and prostate cancer cells." (PMID 33921923, 2021).
colitis (5 papers, 2018 to 2025). Inflammation of the colon. "And mbd2-deficient mice exhibit chronic intestinal inflammation following a single mucosal injury, with MBD2-deficient intestinal T cells overexpressing IFN-γ in experimental colitis." (PMID 40533455, 2025). "Additional studies revealed that mice deficient in Mbd2 manifest increased colitis severity by enhancing the activity of pro-inflammatory macrophages and DCs along with overproduction of type 1 cytokines." (PMID 34420035, 2022). "Strikingly, restriction of Mbd2 deficiency to CD11c+ cells resulted in an exacerbated IL-β+ monocyte mediated colitis." (PMID 32117307, 2020). "In summary, the Mbd2−/− mouse is highly susceptible to DSS‐induced colitis, at least in part, due to the loss of Mbd2 function specifically within the CD4+ cells and loss of appropriate regulation of the pro‐inflammatory cytokine Ifng." (PMID 29603746, 2018). "Additionally, MBD2 deficiency exacerbates DSS-induced colitis by limiting the regulatory capacity of CD11c+ dendritic cells and colonic ECs (Epithelial cells)." (PMID 40533455, 2025). "Collectively, these data show that CD11c-restricted Mbd2 deficiency resulted in increased severity of experimental colitis, characterized by elevated infiltration of IL-1β producing neutrophils and monocytes but equivalent numbers of LP T cells and colon IFN-γ transcript." (PMID 32117307, 2020). "Thus, Mbd2 was required to prevent increased colonic inflammation involving augmented weight loss, diarrhea, pan colitis, tissue architecture destruction, and an immune cell infiltrate characterized by pro-inflammatory cytokine secreting monocytes and neutrophils." (PMID 32117307, 2020). "In addition, we have shown that Mbd2 deficient intestinal T cells over-express IFN-γ in experimental colitis, that Mbd2 deficient mice develop chronic intestinal inflammation after a single mucosal injury, and Mbd2 deficient dendritic cells (DCs) are less able to initiate immune responses." (PMID 32117307, 2020). "We found that the severe inflammation that develops in Mbd2−/− mice during DSS driven colitis is accompanied by a large accumulation of IL-1β+ monocytes." (PMID 32117307, 2020). "Mbd2−/− mice displayed dramatically worse pathology than wild type controls during dextran sulfate sodium (DSS) induced colitis, with increased inflammatory (IL-1β+) monocytes." (PMID 32117307, 2020). "Monocytes are a key pro-inflammatory cell in human and murine colitis, however colon monocytes isolated from Mbd2−/− mice displayed dysregulation of only a handful of genes and similar per-cell cytokine producing capabilities compared to controls." (PMID 32117307, 2020). "In summary, Mbd2 is required for limiting colitis severity via the regulation of both myeloid and epithelial responses in the colon, employing multiple layers of cellular control that cumulatively prevent excessive inflammation in the intestines." (PMID 32117307, 2020). "To test the relevance of these observations, we utilized CD11c-restricted Mbd2 depletion (CD11cΔMbd2 mice), which resulted in increased susceptibility to DSS colitis compared to Cre− controls." (PMID 32117307, 2020). "In summary, these data suggest that Mbd2 plays a dual role in limiting experimental colitis by regulating both CD11c-mediated myeloid cell, and CEC-mediated CD8+ T-cell, colon infiltration." (PMID 32117307, 2020). "Therefore, to understand whether cDC1 or macrophage Mbd2 deficiency was important for the increased susceptibility of Mbd2−/− mice to DSS colitis, we performed microarray analysis on purified CD11b−CD103+ DCs and macrophages from WT and Mbd2−/− DSS treated mice." (PMID 32117307, 2020). "Thus, in a combined model of Mbd2−/− colitis susceptibility (Graphical Abstract), we speculate that at the onset of intestinal inflammation, the Mbd2 deficient epithelium leads to further intestinal damage, through Cxcl9 driven CD8+ T-cell recruitment and EC-MHC-II upregulation." (PMID 32117307, 2020).
colitis (continued). "Next, we demonstrated, using the DSS colitis model, that non‐epithelial roles of Mbd2 are key in preventing the transition from acute to tumour‐promoting chronic inflammation." (PMID 29603746, 2018). "Further investigation of Mbd2 functions should aid at understanding the links between a type 1 acute inflammatory response (the DSS‐induced colitis model) and an anti‐tumour response." (PMID 29603746, 2018). "EtOH failed to alter the level of mBD-2 mRNA in colon or ileum, but it blocked colitis-induced expression of mBD-2 both in colon and ileum." (PMID 30389960, 2018). "We have previously shown that Mbd2 deficiency in ECs using an inducible Cre model does not increase susceptibility to colitis." (PMID 32117307, 2020). "Consequently, restriction of Mbd2 deficiency to CD11c+ dendritic cells and macrophages, or to ECs, resulted in increased DSS colitis severity." (PMID 32117307, 2020). "At 30 days, 83% (5/6, p = 0.002) of Mbd2−/− mice showed continuing signs of colitis which included severe mucosal inflammation with severe diarrhoea, widespread crypt loss, superficial ulceration, focal active cryptitis with scattered crypt abscesses, and patches of epithelial regeneration." (PMID 29603746, 2018). "However, future dedicated investigation and validation of the function of these genes in DCs, and determining whether these are regulated by the action of Mbd2, may shed light on the downstream mechanisms that influence intestinal pathology during colitis." (PMID 32117307, 2020). "In contrast the Mbd2−/− mice failed to resolve the inflammation and developed a chronic mucosal colitis." (PMID 29603746, 2018). "This suggested that, while Mbd2 expression in CD11c+ cells was important to limit pathology, it also regulated gene expression in other, CD11c negative, cell types to dampen inflammation during colitis." (PMID 32117307, 2020).